MAP2K6 (mitogen-activated protein kinase kinase 6)
Description:
Dual specificity protein kinase which acts as an essential component of the MAP kinase signal transduction pathway. With MAP3K3/MKK3, catalyzes the concomitant phosphorylation of a threonine and a tyrosine residue in the MAP kinases p38 MAPK11, MAPK12, MAPK13 and MAPK14 and plays an important role in the regulation of cellular responses to cytokines and all kinds of stresses. Especially, MAP2K3/MKK3 and MAP2K6/MKK6 are both essential for the activation of MAPK11 and MAPK13 induced by environmental stress, whereas MAP2K6/MKK6 is the major MAPK11 activator in response to TNF. MAP2K6/MKK6 also phosphorylates and activates PAK6. The p38 MAP kinase signal transduction pathway leads to direct activation of transcription factors. Nuclear targets of p38 MAP kinase include the transcription factors ATF2 and ELK1. Within the p38 MAPK signal transduction pathway, MAP3K6/MKK6 mediates phosphorylation of STAT4 through MAPK14 activation, and is therefore required for STAT4 activation and STAT4-regulated gene expression in response to IL-12 stimulation. The pathway is also crucial for IL-6-induced SOCS3 expression and down-regulation of IL-6-mediated gene induction; and for IFNG-dependent gene transcription. Has a role in osteoclast differentiation through NF-kappa-B transactivation by TNFSF11, and in endochondral ossification and since SOX9 is another likely downstream target of the p38 MAPK pathway. MAP2K6/MKK6 mediates apoptotic cell death in thymocytes. Acts also as a regulator for melanocytes dendricity, through the modulation of Rho family GTPases.
Synonyms: SAPKK-3; SAPKK3; MEK6; MKK6; PRKMK6; MAPKK6; CRCMSL
Tractability: Small molecule: a structure with a bound ligand is known; a high-quality ligand is known; it has a high-quality binding pocket; it belongs to a druggable protein family. PROTAC: UniProt records ubiquitination sites on it; ubiquitination databases record sites on it; its protein half-life has been measured; a small molecule that binds it is known.
Target class: STE protein kinase group; Kinase; Enzyme; Protein Kinase; STE protein kinase STE7 family
Safety:
Unwanted effects reported when the protein is acted on. In parentheses: how it was acted on, where the effect was seen, and who reports it.
dermatologic toxicity (source: ClinPGx)
diarrhea (source: ClinPGx)
Gene: Protein-coding gene on chromosome 17 (69,414,683 to 69,553,865, forward strand). Ensembl gene ENSG00000108984.
Subcellular location: Nucleus; Cytoplasm; Cytoplasm, cytoskeleton
Subcellular location (Human Protein Atlas): Nucleoplasm; Cytosol
Pathways (Reactome):
Immune System: Interleukin-1 signaling; NOD1/2 Signaling Pathway; PKR-mediated signaling; activated TAK1 mediates p38 MAPK activation
Cellular responses to stimuli: Oxidative Stress Induced Senescence
Developmental Biology: Myogenesis
Disease: Uptake and function of anthrax toxins
Gene Ontology:
Molecular function: MAP kinase kinase activity; protein binding; protein kinase binding; protein serine/threonine kinase activity; ATP binding; protein kinase activity; protein serine kinase activity; protein tyrosine kinase activity
Biological process: MAPK cascade; p38MAPK cascade; stress-activated MAPK cascade; stress-activated protein kinase signaling cascade; cellular senescence; negative regulation of cold-induced thermogenesis; nucleotide-binding domain, leucine rich repeat containing receptor signaling pathway; regulation of cell cycle; signal transduction; signal transduction in response to DNA damage; bone development; osteoblast differentiation; regulation of intracellular signal transduction
Cellular component: cytosol; nucleoplasm; nucleus; cytoplasm; cytoskeleton
Genetic constraint (gnomAD): Loss-of-function variants: 10 observed, 26.65 expected, observed/expected ratio (o/e) 0.38, 90% interval 0.23 to 0.64. The upper end of that interval is the gene's LOEUF score, 0.64, which puts it in group 2 of 6, group 1 being the genes least tolerant of losing a copy. Missense variants: 114 observed, 269.05 expected, observed/expected ratio (o/e) 0.42, 90% interval 0.36 to 0.5. Synonymous variants: 89 observed, 98.19 expected, observed/expected ratio (o/e) 0.91, 90% interval 0.76 to 1.08.
Homologues: Orthologues: chimpanzee MAP2K6 (99% identical), rabbit MAP2K6 (99% identical), dog MAP2K6 (99% identical), macaque MAP2K6 (99% identical), guinea pig MAP2K6 (99% identical), mouse Map2k6 (98% identical), pig MAP2K6 (98% identical), rat Map2k6 (96% identical), tropical clawed frog map2k6 (93% identical), zebrafish map2k6 (87% identical). Paralogues in human: MAP2K3 (79% identical), STK3 (31% identical), STK4 (31% identical), MAP4K4 (31% identical), MINK1 (31% identical), TNIK (31% identical), MAP4K3 (30% identical), MAP4K2 (29% identical), MAP4K1 (29% identical), NRK (29% identical), PAK2 (29% identical), STK10 (29% identical), and 23 more.